FYCO1 (FYVE and coiled-coil domain autophagy adaptor 1)
Description:
May mediate microtubule plus end-directed vesicle transport.
Synonyms: ZFYVE7; FLJ13335; CATC2; CTRCT18; RUFY3
Tractability: PROTAC: ubiquitination databases record sites on it; its protein half-life has been measured.
Gene: Protein-coding gene on chromosome 3 (45,917,903 to 45,995,838, reverse strand). Ensembl gene ENSG00000163820.
Subcellular location: Cytoplasmic vesicle, autophagosome; Endosome; Lysosome
Subcellular location (Human Protein Atlas): Vesicles
Gene Ontology:
Molecular function: protein binding; metal ion binding
Biological process: plus-end-directed vesicle transport along microtubule; positive regulation of autophagosome maturation
Cellular component: autophagosome; late endosome; lysosome; membrane; endosome
Genetic constraint (gnomAD): Loss-of-function variants: 116 observed, 159.88 expected, observed/expected ratio (o/e) 0.73, 90% interval 0.62 to 0.85. The synonymous counts are far from expectation, so gnomAD's model fits this gene poorly and the ratio says little. Missense variants: 1,662 observed, 1,839.5 expected, observed/expected ratio (o/e) 0.9, 90% interval 0.87 to 0.94. Synonymous variants: 631 observed, 760.74 expected, observed/expected ratio (o/e) 0.83, 90% interval 0.78 to 0.89.
Homologues: Orthologues: chimpanzee FYCO1 (99% identical), macaque FYCO1 (95% identical), rabbit FYCO1 (82% identical), dog FYCO1 (80% identical), rat Fyco1 (77% identical), mouse Fyco1 (76% identical), guinea pig FYCO1 (75% identical), zebrafish fyco1a (41% identical), zebrafish fyco1b (34% identical). Paralogues in human: RUFY4 (12% identical).
Diseases named in the same sentence as FYCO1 in open-access papers:
FYCO1 is named in the same sentence as 34 diseases in open-access papers, as found by Europe PMC text mining. Sharing a sentence is not in itself a finding about the gene and the disease. The quoted sentences say what the papers report.
COVID-19 (42 papers, 2020 to 2025). A disease caused by infection with severe acute respiratory syndrome coronavirus 2. "Corroborating this, another study identified a potential causal relationship between the expression of several genes – including FYCO1 in specific immune cell types – and susceptibility to or severity of COVID-19." (PMID 40543387, 2025). "In summary, FYCO1 has been recognized as a key genetic mediator of heightened susceptibility and adverse outcomes in COVID-19." (PMID 40543387, 2025). "We also sought to better understand the pathogenesis of severe COVID-19 and used the AlphaFold v2.0 system to closely examine the tertiary structure of the FYCO1 protein that had mutations in its coding region." (PMID 37547597, 2023). "The most significant locus associated with hospitalization in the COVID-19 GWAS encompassed the FYCO1 and LZTFL1 genes on chromosome 3." (PMID 35648852, 2022). "Gene rankings also inform the interpretation of COVID-19 GWAS results, implicating FYCO1 over other nearby genes in a disease-associated locus on chromosome 3." (PMID 33339864, 2020). "Of additional interest in the context of COVID-19, FYCO1 is associated with the levels of the monocyte chemoattractant protein-1, which contributes to COVID-19 through hyperinflammation." (PMID 33231169, 2020). "In a study correlating gene and protein expression of 17 COVID-19 susceptibility genes with lung cancer prognosis, it was found that the hyperexpression of FYCO1, CXCR6, XCR1, and TAC4 in cancer cells was protective, whereas that of TMEM65 and OAS1 was a risk factor for SARS-CoV2 infection." (PMID 41375068, 2025). "Moreover, we identified a strong association signal located near the FYCO1 gene (lead SNPs: rs71325101 for critical COVID-19, Pmeta=1.02×10-34; rs13079478 for COVID-19 hospitalization, Pmeta=1.09×10-25)." (PMID 37398645, 2023). "Our findings suggest that FYCO1 may accelerate viral intracellular replication and excessive exocytosis and may contribute to an increased risk of severe COVID-19." (PMID 37547597, 2023). "For example, three coding variants of FYCO1 are associated with COVID-19 severity." (PMID 35648852, 2022). "Although all the FYCO1 variants detected in our COVID-19 positive individuals are missense and likely benign variants, we hypothesize that such variants might modulate the intracellular clearance in damaged tissues and clog the cell, worsening tissue damage." (PMID 36228008, 2022). "FYCO1 has molecular interactions with small GTPases from the Ras superfamily and is a candidate gene in a 3p21.31 gene cluster significantly associated with susceptibility to acute respiratory failures during COVID-19." (PMID 34440765, 2021). "Notably, gene mutations altering the tertiary structure of the FYCO1 protein were associated with increased viral replication and spread via enhanced exocytosis, which could explain the severity of COVID-19." (PMID 41375068, 2025). "According to GeneAtlas, FYCO1 variant rs33910087 is a highly significant modifier of monocyte percentage (p = 3.85 × 10−46), and based on GTEx v8, this variant is also an eQTL for several protein-coding genes previously associated with COVID-19 (CXCR6, FYCO1, SLC6A20, CCR1, LZTFL1)." (PMID 35910207, 2022). "Similarly, MR-JTI showed causal support for FYCO1 in lung on COVID-19 severity." (PMID 35318325, 2022). "We did not observe changes in the expression of any of the six genes clustered in the locus associated with respiratory failure in patients with COVID-19 (CCR9, SLC6A20, LZTFL1, CXCR6, XCR1, FYCO1)." (PMID 40722786, 2025). "A severe COVID-19 GWAS Group has identified genetic variants linked to genes such as SLC6A20, LZTFL1, CCR9, FYCO1, CXCR6, and XCR1 in patients experiencing respiratory failure due to COVID-19." (PMID 40143318, 2025). "A recent study developed by our research group investigated genetic variants present in the genes SLC6A20, LZTFL1, CCR9, FYCO1, CXCR6, XR1 and ABO involved with the severity of COVID-19 in indigenous people." (PMID 38543725, 2024).
COVID-19 (continued). "A gene-based association test revealed a significant association in BAZ2B and in previously known COVID-19 risk loci: LZTFL1, XCR1, FYCO1, CCR9, and IFNAR2." (PMID 39361370, 2024). "We found six genes at locus 3p21.31 significantly associated with severe COVID-19: LZTFL1, FYCO1, XCR1, CCR9, TMLHE-AS1, and SCYL2." (PMID 37547597, 2023). "We found significant associations between COVID-19 and LZTFL1, FYCO1, XCR1, CCR9, TMLHE-AS1, and SCYL2 at 3p21.31." (PMID 37547597, 2023). "The first COVID-19 genome-wide association study identified the 3p21.31 gene cluster, including “SLC6A20, LZTFL1, CCR9, FYCO1, CXCR6, and XCR1” as a genetic susceptibility locus in severe patients with COVID-19 and respiratory failure." (PMID 37521836, 2022). "This study aimed to associate genetic variants in the SLC6A20, LZTFL1, CCR9, FYCO1, CXCR6, XCR1, and ABO genes with the risk of severe forms of COVID-19 in Amazonian Native Americans, and to compare the frequencies with continental populations." (PMID 35455670, 2022). "The eQTL analysis encompassing 22 lead SNPs identified 29 novel genes in addition to 4 genes (i.e., SLC6A20, FYCO1, CXCR6, CCR1) previously reported by the severe COVID-19 GWAS group to be associated with rs11385942 at locus 3p21.31." (PMID 34027315, 2021). "Two loci associated with respiratory failure in COVID-19 were found, one of which was the GA-G insertion-deletion variant in locus 3p21.31 that is composed of six genes (SLC6A20, LZTFL1, CCR9, FYCO1, CXCR6, and XCR1)." (PMID 33791232, 2021). "Another study found that the genetic predisposition to colorectal or lung cancer was causally associated with a decreased or increased susceptibility to COVID-19 severity, respectively, and this association pointed to the LZTFL1, CCR9, FYCO1, CXCR6, XCR1, and ABO genes." (PMID 41375068, 2025). "Through an integrative approach involving protein-protein interactions, GWAS, and transcriptomic analyses, researchers have begun to unravel the complex relationship between FYCO1 expression and disease progression, offering valuable insights into the genetic determinants of COVID-19 severity." (PMID 40543387, 2025). "Currently, there is no data on how the detected severe COVID-19-associated polymorphisms in FYCO1 affect protein function, its activity, or intermolecular interactions within the cell." (PMID 37547597, 2023). "Also, recently, it was found that a region of our DNA situated on chromosome 3 (locus 3p21.31), spanning a length of 49.3 kb, consisting of 6 genes (SLC6A20, LZTFL1, CCR9, FYCO1, CXCR6, and XCR1), was associated with the risk of developing severe COVID-19." (PMID 37929242, 2023). "The present study investigated genetic variants in the SLC6A20, LZTFL1, CCR9, FYCO1, CXCR6, XCR1, and ABO genes that are potentially related to severe forms of COVID-19 in Amazonian Native American populations, and compared their frequencies with continental populations." (PMID 35455670, 2022). "Additionally three genes (CCR1, FYCO1, and XCR1) were not only associated with COVID-19, but also at least two cardiac traits." (PMID 36187959, 2022). "The first GWAS analysis with 1980 patients with COVID-19 identified two loci associated with the most severe forms of COVID-19: one locus was 3p21.31, which includes the genes SLC6A20, LZTFL1, CCR9, FYCO1, CXCR6, and XCR1, while the other was 9q34.21, including the ABO blood group." (PMID 35455670, 2022). "This locus contained six genes (SL6A20, LTZFL1, CCR9, FYCO1, CXCR6 and CXR1) that could all plausibly be linked to COVID-19 pathophysiology on the basis of their known functions." (PMID 33339864, 2020). "We corroborate some of the previous findings, provide broadly applicable data from a large previously unrepresented population, present a simplified method for calculating PRSs, and provide data on changes in the FYCO1 gene, which may be a major contributor to severe COVID-19." (PMID 37547597, 2023).
COVID-19 (continued). "The first and most significant locus described in GWAS associated with COVID-19 critical is 3p21.31, which encompasses six genes (SLC6A20, LZTFL1, CCR9, FYCO1, CXCR6, and XCR1) (The Severe COVID-19 GWAS Group, 2020)." (PMID 38226654, 2024). "Finally, two GWAS have identified the loci 3p21.31 (LZTFL1, SLC6A20, CCR9, FYCO1, CXCR6, and XCR1) and 9q34.2 (ABO) with COVID-19 severity." (PMID 33868239, 2021). "Given that LZTFL1 may not be the only gene involved in COVID-19 vulnerability, our data implicating FYCO1 as an additional monocyte candidate gene of the chromosome 3 GWAS susceptibility locus also deserve further consideration." (PMID 35648852, 2022).
cataract (11 papers, 2014 to 2023). Partial or complete opacity of the crystalline lens of one or both eyes that decreases visual acuity and eventually results in blindness. "We then focused on two highly expressed proteins in the lens with an important number of putative SQ/TQ sites and whose mutation causes the development of cataracts: Pax6 (3 SQ/2 TQ) and FYCO1 (10 SQ/6 TQ)." (PMID 37626928, 2023). "The current study reports a novel splice site mutation in FYCO1 gene segregating in autosomal recessive manner with Congenital Cataract." (PMID 35638468, 2022). "It has been also shown that mutations in the autophagy gene FYCO1 (FYVE and coiled coil domain containing 1) cause autosomal recessive congenital human cataract and that autophagy and mitophagy have a role in ocular lens organelle degradation." (PMID 24741567, 2014). "We also analyzed all published mutations of FYCO1 causing cataracts." (PMID 37629644, 2023). "At least 37 different pathogenic FYCO1 variants were identified in patients with cataracts." (PMID 35205377, 2022). "In particular, the FYCO1-related cataract was identified in the Wirehaired Pointing Griffon, a breed that is very similar to the Spinone Italiano." (PMID 37570247, 2023). "Our data enable genetic testing to prevent the unintentional breeding of affected puppies and provide a potential spontaneous large animal model for FYCO1-related cataract." (PMID 35205377, 2022). "In the present study, we demonstrated that disrupting the FYCO1 gene in mice resulted in cataract formation." (PMID 34215815, 2021). "The role of FYCO1 in inherited cataracts has been confirmed in mouse models." (PMID 36766820, 2023).
congenital cataracts (8 papers, 2014 to 2023). "Autosomal recessive congenital cataracts are also linked to mutations in the scaffolding protein FYCO1, which is important in the transport of autophagic vesicles by microtubules." (PMID 36766820, 2023). "Mutations in the scaffolding protein FYCO1, which functions in the transport of autophagic vesicles along microtubules, result in autosomal recessive congenital cataracts." (PMID 36766820, 2023). "As compared to other genes, involved in eye disorders, little information is available in literature about variants of FYCO1 (MIM#607182) in congenital cataracts." (PMID 35638468, 2022). "The current study is aimed to explore the role of the FYCO1 (MIM#607182) gene in causing congenital cataracts in Pakistani families with a focus particularly on autophagy in maintaining the transparency of the lens." (PMID 35638468, 2022). "Some of them, like FYCO1 gene, are involved in lens development and differentiation; also, mutations in FYCO1 gene relate to the development of congenital cataracts." (PMID 29147580, 2017). "Mutations in the autophagy-regulating gene encoding FYVE and coiled-coil domain containing 1 (FYCO1) cause autosomal recessive congenital cataracts." (PMID 27294265, 2016). "Mutations in FYVE and coiled-coil domain containing 1 protein (FYCO1) cause human congenital cataracts and this has implicated autophagy in lens formation and/or function." (PMID 25406393, 2014).
respiratory failure (7 papers, 2021 to 2025). The significant impairment of gas exchange within the lungs resulting in hypoxia, hypercarbia, or both, to the extent that organ tissue perfusion is severely compromised. "Different human polymorphisms have an impact on clinical outcomes: sequence changes in ApoE, TLR7, TMEM189-UBE2V1, as well as SLC6A20, LZTFL1, CCR9, FYCO1, CXCR6, XCR1, have been associated with severe disease outcomes as well as respiratory failure." (PMID 35207458, 2022).
breast carcinoma (3 papers, 2019 to 2026). "Interestingly, siRNA and shRNA-mediated knockdown of FYCO1 also sensitized resistant T47D breast carcinoma cells to TNFSF10/TRAIL-induced caspase activation and cell loss, suggesting that FYCO1 neutralization can also sensitize primarily resistant cells to the death ligand." (PMID 37418591, 2023).
heart failure (2 papers, 2023). Inability of the heart to pump blood at an adequate rate to meet tissue metabolic requirements. "Since overexpression of FYCO1 prevents cardiac dysfunction in response to biomechanical stress, enhancing autophagic flux by overexpressing FYCO1 could be a promising therapeutic strategy to treat or prevent heart failure." (PMID 37234771, 2023).
Allergy (1 paper, 2019). An allergy is an immune response or reaction to substances that are usually not harmful. "Using variant-based analyses, FYCO1, CXCR6 and NRP2 shed new light to mechanisms influencing allergy." (PMID 30206357, 2019).
Azoospermia (1 paper, 2022). Absence of any measurable level of sperm,whereby spermatozoa cannot be observed even after centrifugation of the semen pellet. "Furthermore, CREBP has been suggested to play a role in azoospermia and FYCO1 was also observed recently to be involved in the regulation of the chromatoid body, which is crucial for spermatogenesis, through autophagy." (PMID 36140773, 2022).
bladder cancer (1 paper, 2020). "FYCO1 has also been implicated in colorectal cancer progression and recent studies have concluded that FYCO1 may serve as a biomarker in bladder cancer or hepatocellular carcinoma (Vongchan and Linhardt, 2017)." (PMID 32850870, 2020).
cardiomyopathy (1 paper, 2024). A disease of the heart muscle or myocardium proper. "We consider the regulation of Pip4k2c, Ehmt2, Gper1, Dicer 1, Cul4b, Fyco1, Gn3l and TNNT2 in the context of doxorubicin-induced cardiomyopathy as particularly relevant." (PMID 39285385, 2024).
diabetes (1 paper, 2025). "HIIT, vitamin D3 injection, and their combined treatment significantly decreased the levels of Beclin-1, Fyco-1, and cathepsin D and increased the levels of mTOR and pmTOR compared to the diabetes control group (p < 0.001)." (PMID 40144137, 2025).
diabetic cardiomyopathy (1 paper, 2023). Diabetic cardiomyopathy is a disorder of the heart muscle in people with diabetes. "In the current study, excessive autophagy causes increased protein levels of ULK1, Beclin1, LC3II, Cathepsin D, and Fyco1 in diabetic cardiomyopathy, indicating the important role of these proteins in different stages of the autophagy process." (PMID 37764807, 2023).
dilated cardiomyopathy (1 paper, 2021). Cardiomyopathy which is characterized by dilation and contractile dysfunction of the left and right ventricles. "Upregulation of miR-106b-5p has been demonstrated in myocardial tissue with dilated cardiomyopathy in which the autophagy mechanism is mediated through the miR-106b-5p/FYCO1-dependent pathway." (PMID 33670982, 2021).
inclusion body myositis (1 paper, 2023). A slowly progressive degenerative inflammatory disorder of skeletal muscles characterized by late onset weakness of specific muscles and distinctive histopathological features. "Mutations in FYCO1, for example, were associated with inclusion body myositis and were shown to be increased in VCP patients." (PMID 37371072, 2023).
liver cancer (1 paper, 2021). An epithelial or non-epithelial malignant neoplasm that arises from the liver. "In summary, this study has demonstrated that Nlp was involved in autophagy and promoted the formation of autophagolysosome through facilitating the interaction between Rab7 and FYCO1, which was implicated with tumorigenesis of liver cancer." (PMID 33859171, 2021).
paraplegia (1 paper, 2023). Complete paralysis of the lower half of the body including both legs, often caused by damage to the spinal cord. "FYCO1 also has interaction potential with CCZ1B involved in vacuolar transport, ZFYVE27 (the spastic paraplegia gene), CXCR6, and SASS6 involved in centriole duplication." (PMID 37629644, 2023).
viral infection (1 paper, 2022). "Altogether, our data confirm that FYCO1 is most likely a susceptibility gene and that the more variants are carried by the host, the higher is the susceptibility to viral infection." (PMID 36228008, 2022).
cancer (3 papers, 2018 to 2022). A tumor composed of atypical neoplastic, often pleomorphic cells that invade other tissues. "In cancers, such as squamous cell carcinoma, FYCO1 mediates microtubule-dependent autophagosome transport and maturation, and regulates post-mitotic midbodies degradation." (PMID 35806366, 2022). "Importantly, FYCO1 is downregulated in many aggressive cancers, and FYCO1 knock-down leads to MB accumulation and increase in cancer cell aggressiveness." (PMID 30344284, 2018).
infection (3 papers, 2021 to 2026). The state of being infected such as from the introduction of a foreign agent such as serum, vaccine, antigenic substance or organism. "Host gene variants involved in trafficking (FYCO1 and RAB7A) and immune signaling (FOXA2, SFTPD, STAT3, and TET2) were associated with differential infection profiles." (PMID 41683583, 2026). "Furthermore, in addition to nonsynonymous differences in LZTFL1, CCR9, FYCO1, and SLC6A20A/B, regulatory differences were seen for genes in this locus at baseline as well as in the context of infection." (PMID 35862771, 2022).
FYCO1 also shares sentences with these, for which no sentence is quoted: tumor (2 papers); acute respiratory failure (1); Alzheimer disease (1); asthma (1); autosomal recessive congenital cataract-2 (1); cervical cancer (1); colon carcinoma (1); colorectal cancer (1); hepatocellular carcinoma (1); lung carcinoma (1); neurodegenerative disease (1); ovarian carcinoma (1); prostate carcinoma (1); Sepsis (1); Type 2 Diabetes (1).